ARID2 (AT-rich interaction domain 2)
Description:
Involved in transcriptional activation and repression of select genes by chromatin remodeling (alteration of DNA-nucleosome topology). Required for the stability of the SWI/SNF chromatin remodeling complex SWI/SNF-B (PBAF). May be involved in targeting the complex to different genes. May be involved in regulating transcriptional activation of cardiac genes.
Synonyms: BAF200; KIAA1557; DKFZp686G052; FLJ30619; SMARCF3; ZIPZAP; p200; CSS6
Tractability: Small molecule: a structure with a bound ligand is known. Antibody: its Gene Ontology location is reachable by antibodies, with high confidence. PROTAC: UniProt records ubiquitination sites on it; ubiquitination databases record sites on it; its protein half-life has been measured.
Gene: Protein-coding gene on chromosome 12 (45,728,910 to 45,908,040, forward strand). Ensembl gene ENSG00000189079.
Subcellular location: Nucleus
Subcellular location (Human Protein Atlas): Nucleoplasm
Pathways (Reactome):
Chromatin organization: Formation of the polybromo-BAF (pBAF) complex; RMTs methylate histone arginines
Gene expression (Transcription): RUNX1 interacts with co-factors whose precise effect on RUNX1 targets is not known
Gene Ontology:
Molecular function: ATP-dependent chromatin remodeler activity; DNA binding; protein binding
Biological process: chromatin remodeling; negative regulation of cell migration; negative regulation of cell population proliferation; positive regulation of double-strand break repair via homologous recombination; positive regulation of cell differentiation; positive regulation of double-strand break repair; positive regulation of myoblast differentiation; positive regulation of T cell differentiation; regulation of G0 to G1 transition; regulation of G1/S transition of mitotic cell cycle; regulation of mitotic metaphase/anaphase transition; regulation of nucleotide-excision repair; regulation of transcription by RNA polymerase II; regulation of DNA-templated transcription
Cellular component: nucleoplasm; SWI/SNF complex; chromatin; kinetochore; nuclear matrix; RSC-type complex; nucleus
Genetic constraint (gnomAD): Loss-of-function variants: 29 observed, 176.28 expected, observed/expected ratio (o/e) 0.16, 90% interval 0.12 to 0.22. The upper end of that interval is the gene's LOEUF score, 0.22, which puts it in group 1 of 6, group 1 being the genes least tolerant of losing a copy. Missense variants: 1,672 observed, 2,256 expected, observed/expected ratio (o/e) 0.74, 90% interval 0.71 to 0.77. Synonymous variants: 820 observed, 798.25 expected, observed/expected ratio (o/e) 1.03, 90% interval 0.97 to 1.09.
Gene-disease validity (ClinGen):
ClinGen rates the evidence that ARID2 causes each of these diseases.
Coffin-Siris syndrome (autosomal dominant): Definitive. Coffin-Siris syndrome (CSS) is a rare congenital multi-systemic genetic disorder characterized by aplasia or hypoplasia of the distal phalanx or nail of the fifth digit, developmental delay, intellectual disability, coarse facial features, and other variable clinical manifestations.
Cancer hallmarks: genome instability and mutations (suppresses); suppression of growth (promotes)
Homologues: Orthologues: chimpanzee ARID2 (99% identical), macaque ARID2 (99% identical), dog ARID2 (97% identical), pig ARID2 (96% identical), mouse Arid2 (92% identical), guinea pig ARID2 (92% identical), rat Arid2 (91% identical), rabbit ARID2 (90% identical), tropical clawed frog arid2 (73% identical), zebrafish arid2 (53% identical), Drosophila melanogaster Bap170 (24% identical), Caenorhabditis elegans swsn-7 (18% identical).
Diseases named in the same sentence as ARID2 in open-access papers:
ARID2 is named in the same sentence as 142 diseases in open-access papers, as found by Europe PMC text mining. Sharing a sentence is not in itself a finding about the gene and the disease. The quoted sentences say what the papers report.
melanoma (64 papers, 2013 to 2026). A malignant, usually aggressive tumor composed of atypical, neoplastic melanocytes. "Consistent with the idea that Arid2 loss can disrupt SWI/SNF activity, Arid2 loss leads to deficient PBAF complex assembly in melanoma cells." (PMID 41481722, 2026). "ARID2 mutations have been reported in many human cancers including hepatocellular carcinoma, melanoma, urothelial cancer, gastric adenocarcinoma, non-small cell lung cancer, and more." (PMID 39857780, 2025). "Cutaneous melanoma patients with ARID2 mutation showed significant enrichment with immune checkpoint infiltration markers, including high expression of CD274 (also known as PD-L1), a well-established response marker for immunotherapy." (PMID 38341515, 2024). "To date, ARID2 mutations have been reported in many human cancers, including melanoma, uroepithelial carcinoma, gastric adenocarcinoma, non-small cell lung cancer, and HCC." (PMID 39054516, 2024). "In melanoma, loss of ARID2 in animal models causes global changes in chromatin accessibility and genomic occupancy of melanoma-specific transcription factors, and enhances the ability of melanoma cells to colonize distal organs in animal models." (PMID 38341515, 2024). "ARID2 mutations affect the immune checkpoint inhibitors in melanoma and are linked to an increased infiltration with CD8+ T cells." (PMID 35334544, 2022). "The prevalence of loss of function mutations in ARID2 suggests it is a tumor suppressor in melanoma." (PMID 35323214, 2022). "Although the tumor-suppressive functions of ARID2 in melanoma are not completely understood, loss of ARID2 has been associated with increased sensitivity to immune checkpoint inhibitors by two independent studies." (PMID 35323214, 2022). "In patient-derived melanoma tumors, low ARID2 expression was associated with increased patient survival when tumors had greater CD8+ T cell infiltration, suggesting ARID2 loss enhances tumor immunity." (PMID 35323214, 2022). "A remaining gap is our understanding of why mutations in genes encoding some SWI/SNF subunits, particularly ARID2, are over-represented in melanoma compared to mutations in genes encoding other subunits with known tumor-suppressor functions such as SMARCB1." (PMID 35323214, 2022). "PBRM1 and BRD7, which are mutated at lower frequency in melanoma than ARID2, were also identified in an unbiased CRISPR/CAS9 screen as modulators of resistance to T cell-mediated killing and sensitivity to immunotherapy." (PMID 35323214, 2022). "ARID1A variants (P650S, P1568S, L2119S, P1562L, G831A, G423E4) and ARID2 variants (D239N, S1489L, P1022S, S297F) were detected in 4 intracerebral melanoma tissues." (PMID 33578810, 2021). "Several large-scale sequencing studies in melanoma identified significantly mutated melanoma genes, such as NF), ARID2, TERT or RAC beside the well-established oncogenes including NRAS, BRAF or KIT." (PMID 33578810, 2021). "ARID2 mutations have been reported in many human cancers including melanoma, urothelial cancer, gastric adenocarcinoma, non-small cell lung cancer, HCC, and more." (PMID 32977645, 2020). "Exome data in melanoma showed a higher LoF mutation burden in ARID2 than expected by chance and nonsense mutations were predicted to lead to truncated proteins lacking the C2H2 zinc finger domain." (PMID 32977645, 2020). "The frequency of ARID2 mutations among different melanoma genetic subtypes ranged from 2% in triple wild-type melanoma to 29% in NF1-mutant melanoma." (PMID 33024276, 2020). "Given the fact that the loss of ARID2 makes melanoma cells more sensitive to immunotherapies, it is now necessary to investigate the role of ARID2 as a biomarker predicting HCC response to immunotherapy." (PMID 32977645, 2020).
melanoma (continued). "ARID2 mutations have also been reported in pancreatic cancer, colorectal cancer, melanoma, and non-small-cell lung cancer." (PMID 26634163, 2015). "Nevertheless, the correlation between immunotherapy response markers and the significant difference in outcomes among the different patient cohorts make a strong case for considering ARID2 mutation cutaneous melanoma patients as ideal candidates for immunotherapy." (PMID 38341515, 2024). "ARID2 mutations in melanoma may alter chromatin accessibility, potentially leading to abnormal transcription by MITF and consequently contributing to melanoma development and progression." (PMID 39727945, 2024). "Finally, association analysis performed on more than 1500 melanoma samples showed that ARID2 mutation correlates with higher immune response markers such as TMB (tumor mutational burden), PDl-1 expression, and dMMR/MSI-H compared to ARID2-WT." (PMID 39340537, 2024). "Melanoma presents a distinct situation, where ARID2 mutations are commonplace." (PMID 38374872, 2024). "Thus, the relationship between SMARCA4 and ARID2 would be a potential target for synthetic lethal therapy, as SMARCA4 and ARID2 are frequently mutated in melanoma." (PMID 36844227, 2023). "Finally, the TT NR patient (#62) had the ARID2 p.Gln1313* pathogenic mutation already described in melanoma." (PMID 36901733, 2023). "Interestingly, the data showed that the ARID2 subunit with missenses and truncating mutations is the most frequently mutated subunit in melanoma and is associated with a UVB mutation signature." (PMID 36844227, 2023). "ARID2 was found mutated in hepatocellular carcinoma, melanoma and lung carcinoma." (PMID 35144623, 2022). "ARID2 mutations are frequent in melanoma, independent from BRAF/RAS mutations status." (PMID 35334544, 2022). "PBAF-specific ARID2 is the most frequently mutated SWI/SNF gene in melanoma." (PMID 35323214, 2022). "The association between ARID2 and immune function has previously been established in melanoma." (PMID 33315984, 2020). "If ARID2 is required for melanocyte-specific enhancer function, loss of function mutations in ARID2 would likely result in melanocyte de-differentiation, a process that has been associated with susceptibility to oncogene transformation and melanoma progression." (PMID 35323214, 2022). "Melanoma-private mutations in genes such as ARID1A, ARID2, PIK3CA, and CDKN2A indicated additional late events contributing to malignant progression." (PMID 41516405, 2026). "Nevi most often harbored canonical MAPK-pathway mutations in BRAF and NRAS, as well as in GRIN2A, while melanomas, along with BRAF and NRAS, frequently carried additional driver alterations in ARID1A, ARID2, CDKN2A, and PTEN." (PMID 41516405, 2026). "These melanoma-private mutations occurred in genes linked to chromatin regulation (ARID1A and ARID2), cell growth (e.g., PIK3CA), cell adhesion (e.g., EPHA2), splicing (SF3B1), angiogenesis (PTPRB), and classic tumor suppressors (NOTCH3, CDKN2A, and PTEN)." (PMID 41516405, 2026). "ARID2 depletion leads to transcription changes in genes regulating melanoma metastasis through BAF redistribution." (PMID 38275886, 2024). "An in vitro study demonstrated that ARID2 acts as an immunomodulator in melanomas, and ARIDS2 knock-out enhances the effect of immune checkpoint inhibitors in melanoma cell lines." (PMID 37373134, 2023). "Knockout of ARID2 sensitizes melanoma to ICIs with increased infiltration of cytotoxic CD8+ T cells." (PMID 37217462, 2023). "ARID2 is a tumor suppressor gene, and its mutants occur in various cancer types, including stomach cancer, melanoma, and colorectal cancer." (PMID 37932340, 2023).
melanoma (continued). "In light of accumulated data, ARID2, ARID1B, SMARCA4 (BRG1), and SMARCA2 (BRM) have the most important mutations in melanoma." (PMID 36844227, 2023). "ARID2 loss resulted in greater infiltration of cytotoxic CD8+ T cells and reduced tumor burden in response to anti-PDL1 antibody in a syngeneic mouse melanoma model." (PMID 35323214, 2022). "A CRISPR-Cas9 screen analysis found that ARID2, BRD7, and PBRM1, components of the PBAF complex, sensitized mouse melanoma cells to T-cell cytotoxicity, and PBRM1-deficient murine melanomas were found to be infiltrated by more cytotoxic T cells." (PMID 36361605, 2022). "The unique functions of ARID2 compared to the other ARIDs (ARID1A and ARID1B) will increase understanding of why ARID2 is more frequently mutated in melanoma." (PMID 35323214, 2022). "ARID2 is part of chromatin remodelling complex and is involved in DNA repair in hepatocellular carcinoma cells and enriched in melanomas." (PMID 33274713, 2020). "Especially, loss-of-function mutation in components of this complex such as ARID2, ARID1A, ARID1B or SMARCA4 are found in 13% of melanomas, suggesting a tumor suppressor role and highlighting the importance of chromatin remodeling in melanomagenesis 72,73." (PMID 32042336, 2020). "Another novel and concordant identified biomarker is doramapimod response (also known as BIRB-796) in ARID2 mutant melanoma cell lines." (PMID 33274713, 2020). "Inactivation of Arid2 in B16-F10 melanoma cells makes them sensitive to T cell-mediated killing and enhances IFNγ response." (PMID 32977645, 2020). "Loss of ARID2 or BRD7 enhanced cytokine secretion in response to IFNγ and sensitized melanoma cells to T cell-mediated cytotoxicity in vitro." (PMID 33409155, 2020). "Particularly, ARID2 and IDH1 genes are involved in chromatin remodelling, which suggests a direct connection between somatic mutations and epigenetic dysfunction in melanoma." (PMID 31861757, 2019). "Of note, it was recently demonstrated that CIMP is prevalent in melanoma patients with specific genetic alterations, including NRAS, ARID2, and IDH1 mutations." (PMID 31861757, 2019). "ARID2 is a subunit of the PBAF chromatin-remodeling complex and has been reported to be mutated in melanoma (7%) and colorectal cancer (13%)." (PMID 27270314, 2016). "In keeping with our data, MECOM, MLL2 (KMT2D), MLL (KMT2A), ARID2, and CUX1 were among the most frequently mutated epigenetic genes in the TCGA and Broad Institute melanoma cohorts." (PMID 26221190, 2015). "Furthermore, ARID2-knockout melanoma tumors were proved to be more sensitive to immunotherapy in a murine model." (PMID 39340537, 2024). "The attenuation of ARID2 is associated with a STAT1‐mediated upsurge in chemokines such as CXCL9, CXCL10, and CCL5, which has implications for melanoma's responsiveness to immune checkpoint inhibitors, specifically enhancing the recruitment and penetration of cytotoxic CD8+ T cells." (PMID 38374872, 2024).
melanoma (continued). "Furthermore, data extracted from TCGA melanoma patients showed that ARID2 mRNA levels correlated with survival depending on CD8+ expression." (PMID 37446319, 2023). "ARID2 was found to be a transcriptional repressor of STAT1 expression in melanoma cells and depletion of ARID2 enhanced the interferon γ response, resulting in increased STAT1 and STAT1 target gene expression, including PDL1 as well as several T cell chemokines." (PMID 35323214, 2022). "This study provided insight into ARID2 disruption in melanoma, by indicating that ARID2 is disrupted early during melanomagenesis and suggesting that it may be tied to UVR." (PMID 35323214, 2022). "Still, it is not clear why ARID2 is so frequently mutated in melanoma compared to other SWI/SNF subunits, including other components of PBAF like PBRM1." (PMID 35323214, 2022). "However, Dr. Wucherpfennig's group found that IFN α/γ responsive genes were significantly up-regulated in ARID2 and PBRM1-deficient B16F10 melanoma cells, leading to enhanced T cell infiltration and regression of murine melanoma." (PMID 34865122, 2021). "In addition, low expression of ARID2 prolonged the survival of melanoma patients with high T cell infiltration." (PMID 34827646, 2021). "ARID2 is a subunit of the PBAF chromatin-remodeling complex, and mutations of this gene have been described in various neoplasms (hepatocellular carcinoma, melanoma)." (PMID 32933053, 2020). "Inactivation of genes able to regulate the chromatin remodeling, including ARID2, may enhance the infiltrate of cytotoxic T cells and sensitize melanoma cells to their killing activity [75•]." (PMID 30218391, 2018). "Notably, ARID2 mutations are prevalent in hepatocellular carcinoma (HCC), melanoma, and NSCLC." (PMID 39727945, 2024). "Moreover, melanoma ranks as the cancer that most frequently displays genetic alterations in ARID2." (PMID 35323214, 2022). "The concept that frequent ARID2 mutations are influencing the immune checkpoint inhibitors, being correlated to increased CD8+ T cells, supports the role of ARID2 as a potential biomarker of therapeutic efficiency of immune checkpoint inhibitors in patients with melanoma." (PMID 35334544, 2022). "In addition, alterations in epigenetic regulators like EZH2, ARID2, and IDH1/2, as well as genomic instability caused by mutations in the DNA damage response (DDR) genes, can lead to the altered transcription of key gene regulators in melanomas." (PMID 34831002, 2021). "Interestingly, two genome-wide sequencing studies reported that mutations in ARID2, another PBAF component, occur in melanoma at a significant frequency and may be driver mutations." (PMID 23480510, 2013). "In our analysis, alterations in genes regulating the SWI/SNF chromatin remodeling complex (LoF ARID2, LoF ARID1A, and SMARCA4) were most frequent in Class 3 melanomas." (PMID 38275886, 2024).